BRD4 (bromodomain containing 4)
Diseases named in the same sentence as BRD4 in open-access papers (continued):
Sharing a sentence is not in itself a finding about the gene and the disease.
glioma (continued). "Another study reported that BRD4 promotes glioma cell stemness via enhancing the activation of WNT/β-catenin signaling (by inducing the miR-142-5p promoter methylation, and for miR-142-5p—Wnt3a as a direct target)." (PMID 36674511, 2023). "SPP-ARV-825s presented a strong BRD4 depletion-related antiproliferation effect, especially on NK-1R-overexpressing glioma cells." (PMID 36839734, 2023). "In the CGGA database, high expression of BRD4 was found to negatively correlate with the prognosis of primary and recurrent gliomas in the mRNAseq-325 dataset." (PMID 36224471, 2022). "BRD4 inhibitors effectively penetrate the blood-brain barrier and target glioma tumor tissue, but have little effect on normal brain tissue." (PMID 36171897, 2022). "BRD4 expression level and overall survival in glioma patients were negatively correlated in public databases." (PMID 36224471, 2022). "Analysis of clinical TCGA low grade glioma and glioblastoma data shows BRD4 gene expression correlates with decreased survival only in IDHmut glioma, while BRD3 gene expression correlates with reduced patient survival only in IDHwt glioma." (PMID 35467128, 2022). "In conclusion, we verified that BRD4 was aberrantly overexpressed after treated with cRGD-P/DOX in glioma cells." (PMID 36157053, 2022). "The inhibition and consumption of BRD4 downregulated Notch1 and suppressed stem cell marker‐related genes in glioma-initiating cells (GICs), which affected the self-renewal ability and tumorigenesis of these cells." (PMID 34540687, 2021). "Further, we analyzed the relationship between BRD4 mRNA expression and glioma histology and GBM subtype." (PMID 33135348, 2020). "In CGGA, lower expression of BRD2/BRD4 and higher expression of BRD3 in the primary glioma datasets was associated with survival superiority of patients." (PMID 33135348, 2020). "A total of 680 TCGA RNA‐s Equation (TCGA‐seq) samples and 281 CGGA RNA‐s Equation (CGGA‐seq) samples were evaluated to investigate the relation between mRNA expression of BET family members BRD2/BRD3/BRD4, and overall survival (OS) in glioma patients." (PMID 33135348, 2020). "We found that the mRNA expression of BRD4 was higher in the proneural and classical subtypes of glioma than in the mesenchymal and neural subtypes." (PMID 33135348, 2020). "For the past 20 years, there has been little progress in clinical trials testing new agents until a novel Brd4 inhibition by JQ1 treatment showed potential in glioma treatment." (PMID 28484091, 2017). "Other cancers including uterine, lung, pancreas, breast, prostate, sarcoma, and glioma showed lower frequencies of BRD4 amplification." (PMID 28881656, 2017). "Inhibition of Brd4 by JQ1 treatment showed potential in the treatment of glioma, however, some cases showed low sensitivity of JQ1." (PMID 28484091, 2017). "The use of BRD4 inhibitors is a potential therapeutic target in gliomas and could be considered in such cases." (PMID 41353556, 2025). "Additionally, BRD4 expression is associated with reduced survival in IDH-mutant gliomas, while BRD3 expression is linked to poorer outcomes in IDH-wildtype gliomas." (PMID 40565099, 2025). "ARV‐825 may play a role in modulating drug resistance by degrading the BRD4 protein, thereby exerting anti‐glioma effects." (PMID 39544152, 2024). "Noteworthily, the degradation of BRD4 by ARV-825 not only induced the apoptosis of glioma cells, but also suppressed the tumor-infiltrated M2 macrophage via inhibiting the transcription of downstream IRF4 promoter and the phosphorylation of STAT6, STAT3, and AKT." (PMID 36839734, 2023). "Recently, BRD4 has been reported to promote cell stemness and progression in glioma." (PMID 36711038, 2023).
glioma (continued). "Therefore, the combination of BRD4 inhibitors and other drugs, optimization of dosage form are expected to be effective strategy to improve the therapeutic effect of BRD4 inhibition on glioma." (PMID 36711038, 2023). "As for BRD4, Venkataraman et al17 have demonstrated an indisputable role in mediating the self‐renewal of cancer cells in c‐Myc‐driven medulloblastomas, which was further observed in gliomas, stomach, and liver tumors." (PMID 35049055, 2022). "The study found that the abnormal expression of BRD4 is related to glioma, and the expression in glioma is significantly higher than that in normal tissue; BRD4 inhibitors effectively penetrated the blood-brain barrier and targeted glioma tumor tissue, but had little effect on normal brain tissue." (PMID 36171897, 2022). "Studies have shown that Bromodomain containing 4 (BRD4) may affect the proliferation and apoptosis of glioma cells through affecting DNA replication in the glioma cell line U251." (PMID 33614284, 2021). "Furthermore, in the MYC-expressing human adult high-grade glioma cell line U305628 we again observed a significant downregulation of CCNB1 after 6 h of BRD4 inhibition via JQ1." (PMID 32843692, 2020). "We then investigated BRD4 expression in glioma in 1013 CGGA samples and 268 GSE16011 samples." (PMID 33135348, 2020). "Therefore, the findings with regard to BRD4-HOTAIR-β-catenin/PDCD4-mediated tumor development provide new insight into the complexity of glioma." (PMID 28187439, 2017). "Therefore, we suggested that Notch1 may mediate glioma TMZ resistance, and T+A@Glu‐NPs can downregulate Notch1 by degrading BRD4 protein, thereby reversing glioma TMZ resistance." (PMID 39544152, 2024). "Moreover, BRD4 has been found to be concentrated at the Notch1 promoter region, thus modulating the Notch1 signaling pathway that is involved in the regulation of the self-renewal and tumorigenicity of glioma stem cells." (PMID 37108181, 2023). "The overexpression of BRD4 in cancer cells can induce abnormal expression of its downstream genes involving some pivotal oncogenes such as c-Myc and Bcl-2, which contributes to the occurrence and development of glioma, acute myeloid lymphoma (AML), breast cancer, and other tumors." (PMID 36157053, 2022). "We therefore conclude that ARV‐825 can degrade BRD4 protein to downregulate the transcription of the Notch1 gene, reversing TMZ resistance in gliomas." (PMID 39544152, 2024). "Several BET proteins, BRD4 and BRD2, have been shown to be overexpressed in gliomas making their inhibition an emerging therapeutic strategy." (PMID 38183103, 2024). "A negative correlation between BRD4 expression and overall survival in glioma patients has been observed, with the novel BRD4 inhibitor GNE987 targeting c-Myc expression and modulating transcription through BRD4 downregulation." (PMID 38481812, 2024). "Our study further showed that oHSV infection induced the recruitment of BRD4 and Rpb1 to the promoters of HSV viral genes in glioma cells." (PMID 38167409, 2024). "Furthermore, mechanistic exploration revealed that T+A@Glu‐NPs degraded the BRD4 protein, leading to the downregulation of Notch1 gene transcription and the inhibition of the Notch1 signaling pathway, thereby augmenting the therapeutic efficacy of glioma chemotherapy." (PMID 39544152, 2024). "BRD4-degrading ARV-825 and doxorubicin were encapsulated together in the nanoparticles and the resulting formulation was applied to treat glioma." (PMID 36839734, 2023). "Among the different tissue types 75% of renal and 83% of CNS cancer cell lines showed a positive correlation of GDF15 and BRD4 induction." (PMID 37495707, 2023). "We found that in BRCA, LUAD, and lower-grade glioma (LGG), BRD4 expression was positively correlated with both poor overall survival (OS) and disease-free survival (DFS)." (PMID 30988278, 2019).
glioma (continued). "Bromodomain containing 4 (BRD4), a BET protein, has been well-studied in glioma and has been demonstrated to bind to the HOTAIR promoter." (PMID 28187439, 2017). "Indeed, the enhanced signatures for c-Myc and BRD4, and the functional protection against two distinct BET inhibitors, driven by D463H over-expression in glioma cells, provides strong evidence that this mutant preferentially interacts with the BRD4 axis." (PMID 41187221, 2025). "However, the study’s findings point to the potential of BETis, particularly those targeting BRD4, as promising therapeutics for IDH-mutant gliomas." (PMID 40565099, 2025). "In addition, ChIP-seq showed enrichment of SE-enriched transcriptional coactivators BRD4 and MED1 at the LINC02454 locus in U87 glioma cells." (PMID 38177123, 2024). "In glioma models in female mice, a BET inhibitor enhances the oncolytic activity of oHSV by impeding IGF2BP3-induced NETosis, reinforcing virus replication through BRD4 recruitment with the CDK9/RPB-1 complex to HSV gene promoters." (PMID 38167409, 2024). "Overall, these data suggest that increased BRD4 activity results in enhanced malignancy only in IDHmut glioma, particularly astrocytomas, whereas increased BRD3 activity results in enhanced survival only in IDHwt glioma." (PMID 35467128, 2022). "Increased expression of BRD4 in glioma cells was observed after being stimulated by cRGD-P/DOX, confirming one of the possible mechanisms of DOX resistance and the synergistic tumor inhibition effect of BRD4 degrading ARV combined with DOX." (PMID 36157053, 2022). "As gliomas are liable to develop drug resistance to TMZ in clinic, we studied whether co‐delivery of a BRD4 inhibitor (OTX) could suppress the tumor cells and re‐sensitize cells to TMZ." (PMID 37325609, 2022). "BRD4 inhibition has been shown to inhibit transcriptional activation of the oncogene c-MYC, which has been poised as particularly important for progression from low grade to high grade IDHmut glioma." (PMID 35467128, 2022). "BRD4 expression was elevated in GBM and negatively correlated with the prognosis of glioma." (PMID 36224471, 2022). "For example, the expression of BRD4 in glioma was significantly higher than that in adjacent normal brain tissue." (PMID 36171897, 2022). "Gliomas have significantly higher BRD2 and BRD4 levels than control tissues, and the mRNA and expression levels of BRD4 are closely related to the tumor subtypes and the overall survival rate of the patients, indicating that I-BET151 can have a therapeutic effect on gliomas." (PMID 34540687, 2021). "In recurrent glioma, BRD4 expression (P < .05), but not BRD2/BRD3 expression (P > .05), resulted in significant differences in OS." (PMID 33135348, 2020). "Importantly, JQ1 is a pan-BET inhibitor, and it is likely that BRD4, or a different BET protein, may regulate the growth and development of gliomas via the VEGF/PI3K/AKT signaling axis." (PMID 38183103, 2024). "In glioma, BRD4 (and not BRD2 or BRD4) sustained the self-renewal of glioma-initiating cells by modulating the Notch1 signaling pathway, and significant inhibition of BRD4 resulted in the loss of stem cell-like properties of glioma cells." (PMID 36674511, 2023). "BETi JQ1 demonstrated significant inhibition of BET activity but limited clinical success, as seen with the withdrawal of the Phase II trial for birabresib (MK-8628, OTX015), a selective inhibitor of BRD2/BRD3/BRD4, due to lack of efficacy in IDH-wildtype gliomas." (PMID 40565099, 2025). "We evaluated BRD4, not BRD2 or BRD3, has value in targeted glioma therapy." (PMID 33135348, 2020). "Here, we validated that BRD4, not BRD2 or BRD3, has value in targeted glioma therapy." (PMID 33135348, 2020).
lymphoma (35 papers, 2013 to 2025). A malignant (clonal) proliferation of B- lymphocytes or T- lymphocytes which involves the lymph nodes, bone marrow and/or extranodal sites. "For example, suberoylanilide hydroxamic acid (Vorinostat, SAHA, a HDAC inhibitor) and (+)-JQ1 (a BRD4 inhibitor) display an impressive efficacy against KSHV-associated lymphomas in cultured cells, animal models, and patients." (PMID 36638143, 2023). "Both histone deacetylases (HDACs) and bromodomain-containing protein 4 (BRD4) are validated as therapeutic targets in KSHV associated lymphomas, strongly supported by the excellent anticancer activity of specific inhibitors for these specialized lymphomas in vitro and in vivo." (PMID 36638143, 2023). "Taken together, our study highlights the advantages of HDACs/BRD4 dual inhibitors as novel and promising agents against these virus-associated lymphomas, and strengthens the potential of an oncolytic strategy for improving treatments of these specific malignancies." (PMID 36638143, 2023). "Treatment of mice xenografted with diffuse large B cell lymphoma with the BRD4 inhibitor JQ1 suppresses lymphoma progression." (PMID 38135679, 2023). "Mechanistic studies of 009P1 and 009P2 demonstrated significantly enhanced viral reactivation, cell cycle arrest and apoptosis in KSHV+ lymphomas through dually targeting HDACs and BRD4 signaling activities." (PMID 36638143, 2023). "Mechanistic studies of these compounds confirmed their dual inhibition of HDACs and BRD4 to induce virus lytic reactivation, cell cycle arrest and apoptosis from lymphoma cells." (PMID 36638143, 2023). "The BRD4 inhibitor OTX015 was linked to pomalidomide to generate ARV-825, which reduced BRD4 in a superior manner to OTX015 alone in lymphoma cell lines." (PMID 34203106, 2021). "As a result, ARV-825 actively recruits BRD4 to cereblon, leading to BRD4 efficient degradation via the proteasome in Burkitt’s Lymphoma cells." (PMID 33643919, 2020). "In order to further improve the response of aggressive lymphoma cells, we explored the effects of romidepsin together with the BRD4 inhibitor JQ1." (PMID 31712669, 2019). "This significant delay in I-BET762 antitumor activity still demonstrated similar protein expression profiles for BRD4 and Myc in comparison with control Eμ-myc lymphomas." (PMID 26658189, 2015). "Screening of Anti-KSHV+ lymphoma activities of newly synthesized HDACs/BRD4 dual inhibitors." (PMID 36638143, 2023). "In a Phase I clinical trial of the BRD4 inhibitor CC-90010 in 67 solid tumor and 2 lymphoma patients, one patient each with astrocytoma or endometrial carcinoma achieves a complete response or a partial response, and six additional patients experience prolonged stable disease." (PMID 38135679, 2023). "After screenings with KSHV+ lymphoma systems, we identified 009P1 and 009P2, a pair of epimers, displaying better anticancer activities for KSHV+ lymphomas than current HDACs or BRD4 inhibitors even at low nanomolar concentrations, and with no visible toxicity on normal cells." (PMID 36638143, 2023). "Although BRD4 may acquire this function at later stages when a lymphoma develops in MLV-infected mice, the tethering mechanism whereby MLV IN binds to BRD4 may point to a role during the retroviral integration step." (PMID 35852337, 2022). "Instead, BET inhibitors directly decrease binding of BRD4 to the PD-L1 promoter in lymphoma cells." (PMID 30185888, 2018). "Also, in line with control Eμ-myc lymphomas, modest effects of BRD4 protein expression were observed, while Myc protein stability was significantly attenuated following I-BET762 treatment." (PMID 26658189, 2015). "NHWD-870 showed robust activities inducing apoptosis and suppressing cell proliferation, with stronger effects than BMS-986158, suggesting that this potent and orally bioavailable BRD4 inhibitor could be used for diverse indications against solid tumors and lymphoma in the clinic." (PMID 32286255, 2020).
lymphoma (continued). "Our further mechanistic studies showed that both new compounds significantly enhanced viral lytic genes expression through dually targeting HDACs and BRD4 signaling, resulting in KSHV+ lymphomas cell cycle arrest and apoptosis." (PMID 36638143, 2023). "There is a number of BRD4 inhibitors available with some in clinical trials such as AZD5153 in relapsed/refractory (R/R) solid tumours and lymphoma, CPI0610 in R/R lymphoma and myelofibrosis, and INCB057643 in several tumour types." (PMID 36333293, 2022). "In the human lymphoma cell line Ly1 DLBCL, 79.1% of H3K27Ac sites overlap with Brd4 and 92.2% of chromatin bound Brd4 is at regions of the H3K27Ac active enhancer mark." (PMID 31815961, 2019). "Because PLK1 has been implicated in molecular cross talk with MYC and volasertib possibly has an inhibitory activity on the BRD4 protein, it is plausible that therapeutic targeting of PLK1 in combination with JQ1 might yield a more favorable therapeutic index in MYC-associated lymphomas." (PMID 30323893, 2018). "This is consistent with previous findings that IBET preferentially targets BRD4 over BRD2 and BRD3, and that lymphoma Raji cells stably expressing a dominant negative BRD4 displayed near identical global effects on gene expression to those treated with the BET inhibitor JQ1." (PMID 38884356, 2024). "In two independent Phase I/II dose-escalation, safety and tolerability studies of the BRD4 inhibitors INCB054329 and INCB057643 in patients with solid tumors or lymphoma, 69 and 134 patients have been recruited to INCB054329 (completed) and INCB057643 (ongoing) studies respectively." (PMID 38135679, 2023). "Pharmacological inhibition of the BET family proteins BRD2, BRD3, BRD4, and BRDt has emerged as a therapeutic approach to target MYC-dependent transcription because BRD4 regulates MYC and a number of other lymphoma-relevant oncogenes (BCL2, CDK4/6, and cyclin D1)." (PMID 35031886, 2022). "Thus, the aim of this study was to investigate the effects of romidepsin alone or in combination with the BRD4 inhibitor, JQ1, in the treatment of aggressive lymphomas, and to identify the molecular mechanisms involved in its effects." (PMID 31712669, 2019). "Because MYC deregulation can occur via different modes, we hypothesized that in distinct lymphoma phenotypes, high-level MYC expression may come under the controls of different transcriptional and epigenetic regulatory mechanisms, which may be sensitive or resistant to JQ1/Brd4 inhibition." (PMID 24466310, 2014). "One of these inhibitors, compound 009 with balanced inhibitory activity on HDACs and BRD4 from independent binding to each enzymes exhibited the synergistic and best anti-PEL potency, while much less toxic to KSHV negative lymphomas as expected." (PMID 36638143, 2023). "In these lymphoma lines, it thus seems that JQ1 treatment regulates CYCLON indirectly through MYC rather than through BRD4 – or indeed through BRD2 and 3 which JQ1 can also inhibits." (PMID 23828858, 2013).